IDH1 (isocitrate dehydrogenase (NADP(+)) 1)
Diseases named in the same sentence as IDH1 in open-access papers (continued):
Sharing a sentence is not in itself a finding about the gene and the disease.
glioma (continued). "Therefore, we describe the reprogramming of the central carbon metabolism associated with the IDH1 mutation in a genetically engineered mouse model which reflects the tumor biology encountered in glioma patients." (PMID 32575619, 2020). "Interestingly, MRS investigations have also identified lactate resonances in both IDH1 and IDH2 brain malignancies, and described IDH2 gliomas as more glycolytic than those harboring the IDH1 mutation." (PMID 32575619, 2020). "CD133 is the primary stem cell factor in glioma, and a determiner of growth for glioblastoma cells in immunocompromised mice, a fact that was reported to be somewhat glioma specific in the context of IDH1 mutated cancers." (PMID 33221817, 2020). "The high tendency of the cells carrying mutated IDH1 to grow as a sphere makes organoids a suitable model for understanding the pathophysiology of this mutation in glioma and may help us develop patient-specific therapies." (PMID 33221817, 2020). "In our study, we found that 21.3% of the glioma patients carried the IDH1 mutation." (PMID 33247679, 2020). "The disparities in the IR spectra could potentially be attributed to the increase in 2HG in the IDH1-mutated glioma tissue, which is known to be elevated in tumour cells with the IDH1 mutation." (PMID 33302429, 2020). "Thus, the addition of more glioma samples with the IDH1 mutation would be beneficial for this analysis, in order to minimise the associated error." (PMID 33302429, 2020). "Our study showed that 21.7% of glioma patients harbored IDH1 mutations." (PMID 32856857, 2020). "Mutations in IDH1 are found in 10% of all gliomas and 80% of secondary gliomas." (PMID 31979318, 2020). "In different grades of gliomas, the expression of BMP2 mRNA in IDH1-mutated gliomas was higher than that in wild-type gliomas (t = 15.374, p = 0.000), and the expression of BMP2 mRNA in 1p19q loss of heterozygosity status was higher than that in the intact (t = 16.329, p = 0.000)." (PMID 33116227, 2020). "Although IDH1 mutation has remained an independent favorable prognostic molecular marker for gliomas, and is more objective and reliable than clinical criteria, all malignant gliomas with various molecular characteristics have the possibility of recurrence after operation." (PMID 31773234, 2020). "IDH1-mutated gliomas are slow-growing brain tumours which progress into high-grade gliomas." (PMID 32218467, 2020). "There are many studies about the role of IDH1 and R132H mutation in glioma." (PMID 33221817, 2020). "Activating EGFR mutations are common in IDH1 wild-type gliomas." (PMID 32727536, 2020). "Despite the increasing awareness of the molecular mechanisms of IDH mutations on cancer metabolism and transformation, it remains elusive as to how metabolic deficient cancers, such as IDH1-mutated glioma, acquire an aggressive phenotype during oncogenic transformation." (PMID 32224866, 2020). "The gliomas described in these conditions are similar to the ones caused by sporadic variants in IDH1 or IDH2 for their frequent location in the frontal lobe and their prevalent histological type: more commonly diffuse low-grade or anaplastic gliomas than glioblastomas." (PMID 33282797, 2020). "Among the 59 gliomas, 33.9% (20/59) had an IDH1 mutation and 66.1% (39/59) were wild‐type IDH1." (PMID 32146731, 2020). "Based on the 2016 WHO classification, MET-PET studies in patients with newly diagnosed gliomas have reported a correlation between MET uptake and IDH1 mutation status, showing that IDH1-wildtype gliomas had significantly higher MET uptake than IDH1-mutant gliomas." (PMID 32382870, 2020). "In addition to chromosomal 1p/19q co-deletion status, IDH1/2 mutation status has also been recognized as a vital diagnostic, prognostic, and predictive biomarker for gliomas." (PMID 33192984, 2020). "In addition, well known glioma biomarker IDH1 mutation status was included in the survival analysis." (PMID 33050332, 2020).
glioma (continued). "We analyzed glioma cases, finding 63.4% had mutations in IDH1/2 genes." (PMID 33552543, 2020). "In this study, we utilized synchrotron-based FTIR microanalysis to probe tissue microarray sections from 79 glioma patients, and distinguished the positive class (IDH1-mutated) from the IDH1-wildtype glioma, with a sensitivity and specificity of 82.4% and 83.4%, respectively." (PMID 33302429, 2020). "Furthermore, we found that the characterizations of IDH mutations in the glioma included IDH1 mutation (p.R132H) and IDH2 mutation (p.R172K)." (PMID 32973641, 2020). "Brain organoids may be able to fuse with glioma neurospheres or single glioma cells carrying the IDH1 mutation." (PMID 33221817, 2020). "Recurrent IDH1/2 mutations were detected in gliomas from grade II to IV, showing that IDH1/2 mutated enzymes are needed in gliomagenesis, hence monitoring D2-HG could be a way of following up the therapy response and early diagnosis of clinical relapse." (PMID 32993063, 2020). "The incidence of IDH1 mutations in grade IV gliomas in our cohort was 15%." (PMID 32005184, 2020). "The elevated level of sPD-L1 after RT suggested that the strategy of a combination of immune checkpoint inhibitors and RT might be promising for glioma patients, especially for those with IDH-1 mutations." (PMID 33224142, 2020). "For example, separate categories have been created based on the presence of alterations such as isocitrate dehydrogenase-wild type 1/2 (IDH1/2) ⁠ and histone 3 mutations, which are frequently found in adult low-grade and pediatric high-grade gliomas, respectively ⁠." (PMID 33059718, 2020). "In total, grades II and III gliomas accounted for 69.6% of IDH1 mutations." (PMID 32856857, 2020). "Among the 124 gliomas, 35.5% (44/124) had a IDH1 mutation, of which 97.7% (43/44) was R132H, and 2.3% (1/44) was R132S; and 2.4% (3/124) had an IDH2 mutation, of which 2 cases had a mutation at site 172 (R172W, R172K), and 1 case had a mutation at site 174 (A174Y)." (PMID 32146731, 2020). "Thus IDH1/2 mutations appear to be a good survival factor in glioma, in particular when associated with MGMT methylation." (PMID 33552543, 2020). "IDH1 mutation earns its reputation also based on the hypothesis that it is the mutation that might drive the lower grade glioma (LGG) trending towards malignancy." (PMID 32964017, 2020). "Analysis of a separate glioma classification system based on IDH1 mutation status and DNA methylation similarly revealed elevated TAMs and neutrophils signatures in one subgroup of IDH1 wild-type (WT) tumors, that was of the MES profile." (PMID 33154756, 2020). "Therefore, the preoperative assessment of IDH1 gene mutations in glioma has important clinical predictive value for the diagnosis and prognosis of glioma patients." (PMID 33163535, 2020). "IDH1/2 mutations have been frequently observed in gliomas, leukemia and cartilaginous tumors." (PMID 31935911, 2020). "In adult gliomas, IDH1 mutations indirectly affect H3K27 or H3K36 methylation." (PMID 32500035, 2020). "Of a total 35 glioma patients, the estimated Kaplan-Meier survival with IDH1 wild type (IDH1 WT) was 13 months (range 11.25 to 14.75 months), while patients with IDH1 R132H mutation (IDH1 R132H) was 29 months (range 11.8 to 46.2 months)." (PMID 33282092, 2020). "We report the establishment a large cohort of unique organoids and patient-derived orthotopic xenografts (PDOX) of various glioma subtypes, including gliomas with mutations in IDH1, and paired longitudinal PDOX from primary and recurrent tumors of the same patient." (PMID 33009951, 2020). "IDH1 mutations are considered early events in tumorigenesis; therefore, the subsequent incorporation of further mutations includes more variability between IDH1 mutant and wild-type gliomas." (PMID 32575619, 2020).
glioma (continued). "The glioma patients with tumors carrying a mutation in IDH1 and chromosome 1p/19q co-deletion could have a prolonged survival." (PMID 33229627, 2020). "Moreover, the low ESR1 expression subtypes enriched IDH1 mutations in glioma, liver cancer, and prostate adenocarcinoma." (PMID 32536040, 2020). "Isocitrate dehydrogenase type 1 (IDH1) usually mutates in the development of a subgroup of gliomas." (PMID 32194541, 2020). "When all samples were divided into IDH1 gene mutated (IDH1mut, n = 18) and IDH1 wild-type (IDH1wt, n = 78) gliomas, we observed a tendency of lower expression of CASC2 in IDH1wt (p = 0.053) and highly significant relationship between higher miR-21 expression and IDH1wt gliomas (p < 0.0001)." (PMID 33120918, 2020). "Recent study found that mutations in IDH1/2 may result in the development of glioma and be independent prognosis factors of glioma." (PMID 33299498, 2020). "IDH1 mutation is lowest in grade 1 glioma that correlates with slow tumor growth and good survival." (PMID 32616845, 2020). "Furthermore, using quantitative and non-quantitatve methods we have observed methylation of the MGMT gene promoter, a hallmark of IDH1 mutant gliomas." (PMID 32946483, 2020). "Recent comprehensive genomic profiling has greatly elucidated the molecular hallmarks of gliomas, including the mutations in isocitrate dehydrogenase 1 and 2 (IDH1 and IDH2), loss of chromosomes 1p and 19q (1p/19q), and epidermal growth factor receptor variant III (EGFRvIII)." (PMID 33521638, 2020). "Then, we analyzed the R132H site of the IDH1 gene, which showed the highest rate of incidence, in the ectoderm group, and found that this point mutation mainly occurred in the glioma cases, including 358 cases of brain lower-grade glioma (LGG) and 23 cases of glioblastoma multiforme (GBM)." (PMID 33308219, 2020). "PET tracer uptake in GBMs is usually higher than that in other grades of gliomas, and this may influence the results in relation to IDH1 mutation status." (PMID 32382870, 2020). "Therefore, this study aims to investigate the effects of MGMTp methylation and IDH1 mutations on amino acid metabolism with [18F]FDOPA PET/computed tomography (CT) in patients with glioma." (PMID 33066633, 2020). "Isocitrate dehydrogenase 1 (IDH1) mutations are associated with improved survival in gliomas." (PMID 31960234, 2020). "Furthermore, DTI p and q maps were subsequently used to predict tumor recurrence patterns and have been correlated with IDH-1 mutation status, a driver mutation of gliomas." (PMID 32658776, 2020). "Although these advances resulted in more refined diagnoses and classifications of glioma tumors, integrating histological and molecular information (e.g., IDH1/2 mutations and 1p/19q codeletion), significant improvements in therapies that truly impact on patient outcomes are still lacking." (PMID 31923345, 2020). "In addition, EVs from the blood and cerebrospinal fluid (CSF) of glioma patients were found to contain transcripts and protein of the mutated epidermal growth factor receptor variant EGFRvIII as well as mutant IDH1 transcripts and DNA." (PMID 32178271, 2020). "Notably, TAU expression is induced by mutant IDH so that TAU protein is increased in IDH1 mutated gliomas and is detected in the majority of tumor cells expressing the most common R132H IDH1 mutation." (PMID 33207722, 2020). "An association between IDH status and amino acid PET parameters has been recently reported in LGG, as the IDH-1/2 wild-type lesions have greater metabolic activity than IDH1/2 mutated lower-grade gliomas in terms of the SUVmax and SUV ratio, even if these results need confirmation in larger studies." (PMID 33081358, 2020).
glioma (continued). "In the present study, we demonstrated a possible metabolic compensation mechanism for IDH1-mutated glioma by elevating mTORC2 and small GTPase activity, which reorganized cytoskeleton and plasma membrane, and facilitated substance uptake via enhanced endocytosis." (PMID 32224866, 2020). "Thus, IDH1/2 genes are mutated in 50–80% of low-grade gliomas and secondary glioblastomas, about 20% of acute myeloid leukemia (AML), 50–60% of chondrosarcomas, about 10% of intra-hepatic cholangiocarcinoma and 10% of melanomas." (PMID 32859092, 2020). "Additionally, we examine the potential for earlier molecular subclassification of tumours by identifying the biomolecular alterations caused by the genetic IDH1 mutation in glioma patient serum." (PMID 33302429, 2020). "IDH1/2 mutations are clearly important prognostic markers in gliomas." (PMID 32547876, 2020). "Most of the IDH1 mutations were found in grade II gliomas (56.5%)." (PMID 32856857, 2020). "IDH1 mutations are associated with the glioma types oligidendrioglioma and astrocytoma." (PMID 33552543, 2020). "As a result, phospholipid metabolism is also altered in gliomas bearing IDH1/2 mutations." (PMID 31847543, 2020). "Correlation between IDH1 mutation and MRI features of glioma." (PMID 32582544, 2020). "Furthermore, we showed that the transcription of SOCS1 and SOCS3 is downregulated in IDH1-mutated glioma cases via methylation, suggesting IDHs mutations can regulate protein turnover." (PMID 32931454, 2020). "Point mutations at codon Arg132 of the IDH1 gene were identified in 21 of 62 (33.9%) gliomas." (PMID 31111685, 2020). "Mutation of genes involved in epigenetic modification may be a candidate, as IDH1/2 mutation reportedly causes high‐methylation phenotype of glioma, so‐called G‐CIMP." (PMID 32406600, 2020). "We investigate whether ML analysis of multiparametric radiomic features from preoperative Magnetic Resonance Imaging (MRI) can predict IDH1 mutation status in patients with glioma." (PMID 33121211, 2020). "For example, IDH1 mutation can cause hyper-methylation in lower grade glioma (LGG)." (PMID 31805986, 2019). "IDH1 mutation is one of the most important genetic alteration in gliomas, which is not only necessary for molecular diagnosis of glioma cases, but is also essential for understanding glioma biology." (PMID 30791455, 2019). "D-2HG accumulated in gliomas with IDH1 mutation in the previous reports." (PMID 31278288, 2019). "IDH1/2 mutations confer a gain of function in glioma cells, resulting in the accumulation and secretion of a vast excess of an oncometabolite, D-2-HG, which ultimately inhibits the catalytic activity of α-KG-dependent dioxygenase, damaging the key steps in histone modification and DNA demethylation." (PMID 31263678, 2019). "This could be of importance, since the somatic mutations found in the IDH1/IDH2 gene are mostly found in low grade gliomas (LGG) and the proneural GBM subtype." (PMID 31574953, 2019). "In view of the important role of IDH1/2 mutations in the occurrence and development of glioma, studies of these proteins may enable researchers to identify appropriate inhibitors and intervene in the treatment of glioma patients with IDH1/2 mutations." (PMID 31263678, 2019). "In astrocytes it could furthermore be demonstrated that vimentin was necessary to maintain their polarization, indicating a possible important role for vimentin in explaining the effects of IDH1 mutations on glioma behavior." (PMID 31242696, 2019). "We thus investigated the mutation frequency of IDH1 in glioma patients." (PMID 32047515, 2019). "A TCGA lower-grade glioma study used comprehensive multiple omics data and unbiased integrative bioinformatics analyses to define three molecular subtypes based on two molecular markers, 1p/19q codeletion and IDH1/2 mutations." (PMID 31788444, 2019).
glioma (continued). "Similarly, in RCAS/tva models of glioma, it has been shown that IDH1 mutations are associated with reduced neutrophil chemotaxis and anti-tumor immunity." (PMID 31632393, 2019). "The use of ‘omic’ analysis for identification of survival features has had the most success in grade II/III glioma where distinct subtypes of gliomas can be defined by combinations of mutations in isocitrate dehydrogenase (IDH1-R132H), telomerase (TERT) and 1p/19q chromosomal co-deletion." (PMID 31405148, 2019). "We recently reported that loss of mutant IDH1 expression is not sufficient to repress tumor growth derived from immortalized human astrocytes expressing doxycycline-inducible mutant IDH1, thus suggesting that IDH1 mutation is dispensable for glioma progression and maintenance." (PMID 31652645, 2019). "IDH1/2 mutations were found in a majority of secondary GBMs (derived from lower-grade tumors), but only 2–3% were found in primary GBMs or pediatric gliomas." (PMID 30857299, 2019). "There is a big survival difference between IDH1-mutated vs. wild-type gliomas." (PMID 31853670, 2019). "As such, our cells might not fully recapitulate the complete metabolic signature associated with IDH1 mutant glioma." (PMID 30833594, 2019). "Therefore, finding a suitable IDH1/2 mutations vaccine will benefit patients greatly and help them escape the magic spell of glioma recurrence." (PMID 31263678, 2019). "The IDH1 mutation has been reported to be a novel driver mutation of gliomas." (PMID 31443404, 2019). "Besides, the expression of ALDOC is not only negatively associated with IDH1, but is also related to better prognosis in gliomas." (PMID 31450822, 2019). "In detail, they found that somatic mutations in IDH1 at R132 or IDH2 at R172 led to increased risk of glioma, hemangiomas and chondrosarcoma, and they demonstrated that the mutated IDH contributed to the increased cell proliferation, colony formation, and inability to differentiate." (PMID 30984620, 2019). "In some low-grade glioma patients, the spontaneous immune response to IDH1 mutation has been found." (PMID 31263678, 2019). "Therefore, downregulation of DUSP4 expression in gliomas is suggested to be caused by epigenetic regulation triggered by IDH1 mutation and to contribute to glioma tumorigenesis through enhancement of MAPK signaling." (PMID 30791455, 2019). "It has been reported that IDH1 mutation predicted better prognosis in glioma." (PMID 31718604, 2019). "IGF2BP3 may be associated with malignant progression of IDH1-mutant gliomas and be a candidate therapeutic target." (PMID 30760837, 2019). "Overall, 14/76 (18.4%) glioma had an isocitrate dehydrogenase 1 (IDH1) mutation." (PMID 31847343, 2019). "Thus, the activation mutation of IDH1/2 in glioma provides a new angle to promote the clinical efficacy of PD-1/PD-L1 checkpoint blockades." (PMID 30777100, 2019). "Although there are some useful molecular markers that may help clinicians make meaningful differentiations between subgroups of gliomas such as IDH-1 mutation status most such factors remain unknown." (PMID 31556016, 2019). "Hence, the improved prognosis and the prolonged overall survival of glioma patients harboring the IDH1 mutation seem to be an interaction between two factors, namely the increased sensitivity to therapy and the reduced aggressiveness of these tumors." (PMID 31242696, 2019). "IDH1 mutations in gliomas are gain-of-function mutations that lead to the generation of the oncometabolite 2-hydroxyglutarate instead of 2-oxoglutarate from isocitrate, which induces a wide range of epigenetic dysregulation collectively termed “glioma CpG island methylator phenotype”." (PMID 30791455, 2019). "Accordingly, the DUSP4 expression level might serve as a predictor of IDH1 mutation, which currently is crucial for the molecular diagnosis of gliomas." (PMID 30791455, 2019).